MBD5 (methyl-CpG binding domain protein 5)
Diseases named in the same sentence as MBD5 in open-access papers (continued):
Sharing a sentence is not in itself a finding about the gene and the disease.
neurodevelopmental disorder (14 papers, 2015 to 2025). A behavioral and cognitive disorder with onset during the developmental period that involves impaired or aberrant development of intellectual, motor, or social functions. "Disruptions in MBD5 have been associated with various neurodevelopmental disorders and MBPs, such as MBD5, are essential for DNA methylation, a critical process in neurogenesis." (PMID 40137900, 2025). "Deletions or loss-of-function variants of MBD5 cause MBD5-associated neurodevelopmental disorder (MAND; OMIM #156200)." (PMID 35205380, 2022). "Mental retardation autosomal dominant 1 (MRD1, OMIM #156200) or MBD5 haploinsufficiency is a neurodevelopmental disorder caused by heterozygous variants in MBD5 or a deletion encompassing all or part of this gene sequence on chromosome 2q23.1." (PMID 33959609, 2021). "Of the children with SPD, 2/11 (18%), were identified as having a de novo loss of function or missense mutation in genes previously reported as causative for neurodevelopmental disorders (MBD5 and FMN2)." (PMID 29801487, 2018). "Microdeletions of 2q23.1 disrupting MBD5 and loss of function mutations of MBD5 cause MBD5‐Associated Neurodevelopmental disorders (MAND)." (PMID 28944244, 2017). "MBD5 haploinsufficiency has been associated with the disruption of primary cilium-related processes during early cortical development, and this has been reported in many neurodevelopmental disorders." (PMID 37628781, 2023). "To understand the potential implications of MBD5 haploinsufficiency on primary cilia, we studied the ciliary length and total cilia count, as these have been identified in other neurodevelopmental disorders." (PMID 37628781, 2023). "Though this association is known, the exact mechanisms through which perturbed MBD5 expression leads to neurodevelopmental disorders remain highly underexplored." (PMID 37628781, 2023). "This case report describes a family harboring two CNV microdeletions, which affect regions of NRXN1 and MBD5 - each well-established in association with risk of ASD and other neurodevelopmental disorders." (PMID 28649445, 2017). "The CNVs involved known disease genes (EHMT1, MBD5 and SCN1A) and imbalances in genomic regions associated with neurodevelopmental disorders (16p11.2, 16p13.11 and 2q13)." (PMID 27113213, 2016). "Consistent with this notion, alterations in the expression of MBD5 gene causes a rare NDD termed MBD5-associated neurodevelopmental disorder (MAND), a general term that encompases 2q23.1 deletion syndrome, 2q23.1 duplication syndrome and MBD5 heterozygous variants." (PMID 36547251, 2022). "We hypothesize that these abnormal transcripts may lead to changes in the amino acid sequence, thereby producing dysfunctional proteins that impair the normal function of the MBD5 protein, ultimately contributing to neurodevelopmental disorders in affected patients." (PMID 40662461, 2025). "This leads us to suggest that reduced dosage of either MBD5 or SATB2 causes neural stem cells to be more characteristic of differentiating cells than proliferating cells, and that this may be a unifying feature of neurodevelopmental disorders more generally." (PMID 25966365, 2015).
cancer (2 papers, 2020 to 2022). A tumor composed of atypical neoplastic, often pleomorphic cells that invade other tissues. "Mutations within MBD5 and MBD6 have been detected in multiple human cancers, as well as neuronal disorders." (PMID 36180891, 2022). "Our results that five epidriver candidates (SRCAP, EP400, ARID1B, MBD5, and KMT2A) among the top 15 ERGs enriched in EMT fraction were found among the most mutated ERGs in clinical samples across cancer types support the driver role of EMT-specific ERG tumorigenesis." (PMID 32963031, 2020). "We characterize MBD5 and MBD6 as important regulators of the BAP1 complex and maintain its transcriptional landscape, shedding light on the therapeutic potential of targeting MBD5 and MBD6 in BAP1-dependent human cancers." (PMID 36180891, 2022). "Among the top most significant EMT-specific hits, one-third belonged to the category of histone methylation writers, whereas several ERGs (including KMT2A, EP400, MBD5, and SRCAP) were found to be frequently targeted by genetic alterations in several cancer types." (PMID 32963031, 2020).
neurological diseases (2 papers, 2020 to 2024). "MBD5, OGDHL, AUTS2, EGR3, QPCT, and ITGA8 are linked to neurological diseases." (PMID 39588153, 2024). "We next compared our genes to gene sets of ASD or other neurological disorders and found that CHD8, DYRK1A, GRIN2B, MBD5 and SCN2A overlapped with the ASD gene sets (FDR ≤ 0.1) reported in previous large-scale ASD studies." (PMID 32193494, 2020).
tumor (1 paper, 2022). "In addition, the MBD5 and MBD6 subunits are critical for maintaining the stability of the BAP1 complex and therefore are essential for BAP1-dependent tumor cell growth in vitro and in vivo." (PMID 36180891, 2022).
MBD5 also shares sentences with these, for which no sentence is quoted: autism (3 papers); psychiatric disorder (3); bipolar disorder (2); microdeletion syndrome (2); Cri-du-chat syndrome (1); depression (1); Down syndrome (1); fragile X syndrome (1); genetic disorders (1); Glucose intolerance (1); Hypoinsulinemia (1); infertile (1); Insulin resistance (1); Kleefstra syndrome 1 (1); metastatic cancer (1); Pitt-Hopkins syndrome (1); psychosis (1); Seizure (1); sleep disorder (1); Tatton-Brown-Rahman syndrome (1).